ANXA3 (annexin A3)
Diseases named in the same sentence as ANXA3 in open-access papers (continued):
Sharing a sentence is not in itself a finding about the gene and the disease.
head and neck cancer (1 paper, 2009). A primary or metastatic malignant neoplasm affecting the head and neck. "Expression of annexin A3 has only been studied in a limited number of tumor types with only one report regarding its expression in head and neck cancer." (PMID 19691830, 2009).
idiopathic pulmonary fibrosis (1 paper, 2024). Idiopathic pulmonary fibrosis (IPF) is a nonneoplastic pulmonary disease that is characterized by the formation of scar tissue within the lungs in the absence of any known cause. "Anxa3 is known to promote immune infiltration through the NF-ΚB signaling pathway and has previously been implicated as a key candidate gene in the progression of idiopathic pulmonary fibrosis." (PMID 39056733, 2024).
infarction (1 paper, 2023). A localised pathological necrosis of tissue resulting from obstruction of the blood supply usually by a thrombus, an embolus, or vascular torsion. "The silencing of ANXA3 would promote repair and healing of the myocardium after infarction by the activation of the PI3K/Akt signaling pathway." (PMID 36952494, 2023).
laryngeal carcinoma (1 paper, 2025). Carcinoma that arises from the laryngeal epithelium. "Specifically, it has been found that annexin A3 (ANXA3)-loaded exosomes derived from TAMs impaired ferroptosis process in laryngeal cancer cells supporting lymphatic metastasis." (PMID 39981232, 2025).
liver cirrhosis (1 paper, 2012). "We have specifically identified annexin A3 and annexin A6 as a potential biomarker for predicting alcohol-induced liver cirrhosis." (PMID 22682408, 2012). "Further investigation of the function mechanism of ANXA3 and ANXA6 in liver cirrhosis may yield new clues to the molecular mechanism of alcohol-induced liver disease." (PMID 22682408, 2012).
Lymphatic Metastasis (1 paper, 2017). Transfer of a neoplasm from its primary site to lymph nodes or to distant parts of the body by way of the lymphatic system. "The relative risks of lymphatic metastasis and ANXA3 expression to DFS prognosis were 2.181 and 1.569, respectively, while those relative to OS prognosis were 2.052 and 1.698, respectively." (PMID 28497041, 2017).
meningioma (1 paper, 2025). A generally slow growing tumor attached to the dura mater. "To explore the potential relevance of targeting ANXA3 for higher-grade meningiomas, we extended our investigations to grade 3 meningioma cells." (PMID 40562609, 2025). "Role of ANXA3 in meningioma proliferation being a key factor in NF2−/− meningiomas." (PMID 40562609, 2025). "Our studies using tumour-derived primary cells highlight ANXA3 as an effective therapeutic target, and in vivo findings further support its potential, demonstrating significant effects on cell growth in higher-grade meningiomas." (PMID 40562609, 2025). "Additionally, proteomics identified Annexin-3 (ANXA3) upregulated in NF2−/− meningioma." (PMID 40562609, 2025). "Although ANXA3 is highly expressed in grade 1 and 2 meningioma tissues as observed by Western blot analysis, the NF2 phenotype, characterised by loss of function due to mutations, truncations, and/or deletions, is frequently observed in higher-grade meningiomas or more advanced molecular groups." (PMID 40562609, 2025). "This indicates that ANXA3 inhibition may serve as a promising therapeutic strategy for meningioma providing more specific treatment than conventional chemotherapy and this treatment could be used alongside the conventional treatments used such as radiation and surgical resection in higher grades." (PMID 40562609, 2025). "The clinical application of the first-class ANXA3 inhibitor SL-18 has not been addressed in clinical trials to date, and the validation of an ANXA3-specific inhibitor for in vivo use with meningioma cells remains pending." (PMID 40562609, 2025).
metastatic diseases (1 paper, 2025). "On the other hand, we suggest that drug combinations targeting ANXA3/ANXA6, and ANXA11/ANXA7 might be useful against lung- and liver-metastatic diseases, respectively." (PMID 40410902, 2025).
neuropathic pain (1 paper, 2017). Chronic pain caused by damage to nerve fibers. "A lentivirus delivering ANXA3 shRNA (LV-shANXA3) was administered intrathecally to determine the analgesic effects of ANXA3 on allodynia and hyperalgesia in a CCI-induced neuropathic pain model in rats." (PMID 28928629, 2017).
psychotic disorder (1 paper, 2025). An abnormal condition of the mind that involves a loss of contact with reality. "Considering these data and studies, it is clear that ANXA3 deficiency may be associated not only with psychotic disorders but also with several psychiatric conditions." (PMID 41010398, 2025). "Annexin A3 (ANXA3) is a calcium-binding protein that plays a role in membrane phospholipid metabolism and inflammation, and significant alterations have been shown in some psychotic disorders." (PMID 41010398, 2025). "Annexin A3 (ANXA3) has important functions in widespread activity and membrane phospholipid metabolism, and these functions have been shown to play a role in the pathogenesis of psychotic disorders." (PMID 41010398, 2025).
skin cancer (1 paper, 2018). "The vast heterogeneity of the sample collection with respect to diverse factors like platforms, origin, parts of the body, etc. positively influenced in the finding of 6 genes that had not previously related to skin cancer: SCGB2A1, CRYBA2, ANXA3, PCP4, SOSTDC1 and MYO15A." (PMID 29750795, 2018).
Sleep apnea (1 paper, 2015). An intermittent cessation of airflow at the mouth and nose during sleep is known as sleep apnea. "Interestingly, neither ITGAM nor ANXA3 were altered in either sleep apnea or “sleepy” subjects suggesting that they may be better suited for detecting acute sleep loss than for identifying patients with chronic sleep disruption." (PMID 25873764, 2015).
thrombosis (1 paper, 2023). "Recently, dysregulation of the ANXA3, TNFAIP6, TXK, BACH2, and SERPINB2 genes has been associated with both arterial and venous thrombosis in the general population." (PMID 37035297, 2023).
thyroid (1 paper, 2015). "In addition, our results are contradictory to the results from a previous proteomic study showing significant down-regulation of ANXA3 in classic PTC as compared to normal thyroid, and can indicate different pathophysiological properties between the cystic thyroid lesions and classical PTC." (PMID 25978681, 2015).
thyroid cancer (1 paper, 2018). "However, ANXA3 expression was essentially reduced in prostate and thyroid cancers, and the expression of ANXA3 was negatively correlated with tumor development." (PMID 29374148, 2018).
tuberculosis (1 paper, 2024). A chronic, recurrent infection caused by the bacterium Mycobacterium tuberculosis. "The results of ROC showed that TYMP (AUC = 0.964), LAP3 (AUC = 0.914), ADGRL2 (AUC = 0.98), SIL1 (AUC = 0.936), LMO7 (AUC = 0.856), SULF1 (AUC = 0.96), ANXA3 (AUC = 0.798), and PACSIN3 (AUC = 0.747) had high accuracy in predicting tuberculosis." (PMID 39023413, 2024).
urothelial carcinoma (1 paper, 2018). A malignant neoplasm derived from the transitional epithelium of the urinary tract (urinary bladder, ureter, urethra, or renal pelvis). "Because ANXA3 has been reported to be a biomarker for other urothelial carcinomas, we focused on HSPE1 expression in clinical samples, validating its concentration level in individual urine samples." (PMID 30112103, 2018).
venous thromboembolism (1 paper, 2023). Occlusion of the lumen of a vein by a thrombus that has migrated from a distal site via the blood stream. "We chose to quantify ANXA3, TNFAIP6, TXK, BACH2, and SERPINB2 mRNA expression in t-PAPS based on the results of a meta-analysis using a bioinformatics panel to explore the differences and similarities between venous thromboembolism (VTE) and cardiovascular disease." (PMID 37035297, 2023).
cancer (58 papers, 2010 to 2025). A tumor composed of atypical neoplastic, often pleomorphic cells that invade other tissues. "Membrane-associated protein A3 (Annexin A3, ANXA3) is a member of the membrane-associated protein family involved in membrane trafficking and cancer development." (PMID 38310228, 2024). "ANXA3 was reported to have both diagnostic and prognostic potential in several cancers, including LC54, but only studies with small number of participants have been performed so far53." (PMID 38007577, 2023). "The dysregulation of Anxa3 has been reported to be associated with cancer development and progression." (PMID 35308536, 2022). "Similar to other members of the annexin family, aberrant expression of ANXA3 has been linked to cancer pathogenesis, although it is highly dependent on the tissue of origin." (PMID 36247003, 2022). "Yet, it is important to note that above observations are both based on small sample sizes and that more conclusive data from larger cohorts are still awaited about the role of genetic alterations of the ANXA3 gene in cancer susceptibility." (PMID 34355022, 2021). "So far, very limited evidence has been published reporting the association between genetic alterations of the ANXA3 gene with cancer susceptibility." (PMID 34355022, 2021). "The findings obtained thus far point towards a potential use of ANXA3 as a diagnostic, prognostic and predictive biomarker for cancer patient management." (PMID 32682335, 2020). "Their experiment described differential expression of proteasome subunit alpha type 1 (PSA1), leucine aminopeptidase 3 (LAP3), annexin A3 (ANXA3), and maspin (serpin B5), demonstrating a proteomic profile of antibody-inducing cancer-associated immunogens." (PMID 31828035, 2019). "Most AnxA3-related studies focussed on its potential as a biomarker in several cancers and the association of AnxA3 with chemotherapy resistance, with possible roles in the proliferative and invasive properties of cells." (PMID 31337068, 2019). "ANXA3, a membrane associated protein, has been reported to be abnormally expressed in various cancers." (PMID 29374148, 2018). "We also investigated the potential regulation of cancer-associated signaling pathways by Anxa3 through screening for the altered expression of some common signaling molecules after Anxa3 downregulation." (PMID 27995049, 2016). "To explore the biological roles of Anxa3 in LADC, we analyzed the changes in the activation of several important cancer-associated signaling pathways induced by Anxa3 downregulation." (PMID 27995049, 2016). "Annexin A3 (ANXA3) plays a critical role in promoting aggressive cancer and stem cell-like properties in HCC and is involved in mediating the activation of autophagy and attenuation of PKCd (PRKCD)/p38-dependent apoptotic signaling." (PMID 39272847, 2024). "The other altered genes included ABCA12, a transmembrane lipid transporter, required for the proper vesicle trafficking and functioning of secretory granules in cancer cells or ANXA3 which affects the expression of cytokine genes and tumor immune infiltration." (PMID 36604669, 2023). "They observed that cancer cells expressing annexin A3 in high concentration released many exosomes, and exosomes serve as vehicles to transfer annexin A3 between cells to induce drug resistance." (PMID 37497408, 2023). "Despite mounting evidence supporting the involvement of ANXA3 in cancer development and progression, as of yet, very little has been unraveled regarding its specific contribution to HNC." (PMID 36247003, 2022). "Meanwhile, dysregulation of ANXA3 has been reported to play a pivotal role in cancer development and progression." (PMID 34355022, 2021). "Annexin A3 belongs to the phospholipid-binding protein family, which is involved in intercellular interactions and is closely related to cancer cell invasion, metastasis, and chemoresistance." (PMID 34778252, 2021).
cancer (continued). "Intriguingly, an inverse relationship between ANXA3 expression and the execution of invasion-metastasis cascade in malignant tumors has also been documented." (PMID 34355022, 2021). "CAFs increase Annexin A3 (ANXA3) expression in cancer cells, a Ca2+-dependent phospholipid-binding protein with an important role in tumor growth and progression." (PMID 33673405, 2021). "Although ANXA3 expression in many cancer cells seems to correlate directly with the rate of cellular proliferation, the underlying mechanism(s) are undefined." (PMID 32682335, 2020). "ANXA3 correlates also with cell proliferation as indicated by Ki-67 and Bcl-2 expression and appears to be preferentially expressed in cancer stem-like cells/cancer initiating cells (CSCs/CICs)." (PMID 29423100, 2018). "For ANXA3, 7 of 8 patients displayed higher protein expression in cancer, with mean ER of 4.8 across all 8 pairs (third row)." (PMID 29423100, 2018). "In hepatocellular carcinoma, Anxa3-mediated maintenance of cancer stem-like cells activity was revealed to most likely involve the HIF-1α/Notch pathway." (PMID 27995049, 2016). "Collectively, previous findings demonstrate that ANXA3 has an important impact on the migration, invasion, and metastasis of malignant tumors." (PMID 27894078, 2016). "Investigation of the proteins were associated with incidence of cancers, including ZAG, CALR, annexin A2, annexin A3 and Hp." (PMID 24884814, 2014). "Annexin A3 also play roles in cancer dependent autoimmne regulation against angiogenesis, exosomes/prosteasomes, and calcium dependent processes." (PMID 24884814, 2014). "Our results imply the possibility of the involvement of ANXA3 in collateral pathways enabling cancer cells to circumvent TKI therapy." (PMID 23555683, 2013). "Annexin A3 could play an important role in the development, proliferation, migration, and metastasis of malignant tumors and/or tumor cell." (PMID 34750284, 2022). "In this review, we dissect the role of ANXA3 in cancer in detail." (PMID 34355022, 2021). "According to the gathered data in this review, differential expression of ANXA3 has been demonstrated in a wide array of cancers, which is capable of sustaining cell proliferation signaling, promoting invasion and metastasis, inducing angiogenesis and resistance to various chemotherapeutic agents." (PMID 34355022, 2021). "Collectively, aberrant expression of ANXA3 plays a crucial role in malignant tumor development." (PMID 34355022, 2021). "Despite a relatively short DSS administration period, WOL intervention improved the expression levels of cancer-related proteins in the colon (Anxa3 and Co3) as well as oncogenic hepatic genes (Saa1, Jun and S100a8) as observed in the DSSWOL mice as compared to the DSS group." (PMID 32258419, 2020). "These researches demonstrate that ANXA3 may have important impact on the progression and metastasis of different human cancer types." (PMID 27894078, 2016). "Recent studies have shown that Anxa3 might function as either a tumor promoter or suppressor in different cancers." (PMID 27995049, 2016). "ANXA3 also exhibited important roles in tumor development, metastasis and drug resistance and showed up-regulated expression in many active cancers." (PMID 26557426, 2015). "Although the relationship between cancer and rs2867461 in ANXA3 has not been reported to date, many studies have recently been published on the association between ANXA3 and drug resistance or chemotherapy response." (PMID 26475168, 2015). "However, IHC and WB showed similar staining of ANXA3 in all cPTCs, including normal thyroid cells surrounding the cancer, which can be attributed to the diverse biological functions of ANXA3 in normal thyroid cells." (PMID 25978681, 2015). "Annexin A3 was predominantly expressed in the cytoplasm of cancer cells." (PMID 24260057, 2013).
cancer (continued). "Furthermore, serum levels of annexin A3 were higher in platinum-resistant patients, and it is proved that Annexin A3 upregulated in platinum-resistant cells by decreasing intracellular concentration of platinum and inhibiting cancer cell apoptosis." (PMID 37497408, 2023). "However, the mechanism underlying the diminution of 36-kDa ANXA3 in RCC remains unclear, and the differences between the two isoforms regarding their expressions and functions in other cancer models are still far from fully understood." (PMID 34355022, 2021). "The genes which have been reported to involve the cancer cell invasion (ENPP2, ADCY8), dysregulated cellular metabolism (CYC1), and angiogenesis (ANGPT1), immune inhibition (ANXA3) amplified notably in the high-risk group, which might elaborate the aggressiveness and malignancy in this group." (PMID 34568069, 2021). "ANXA3 participates in multiple biological activities, including cell apoptosis, cell proliferation, cell differentiation, signal transduction, anti-inflammatory response, endocytosis and exocytosis, which may contribute to cancer development and metastasis." (PMID 29423100, 2018). "ELF3, which is predicted to drive the expression of highly expressed ID genes ANXA3, TGFB2, and duct marker KRT8, has been shown to drive ligand-independent transactivation of CTNNB1 in cancer models." (PMID 36540608, 2022). "Annexin A3 (ANXA3), an important member of the Annexin multigene family, plays a pivotal role in signaling pathways and malignant biological behaviors of cancer cells, such as proliferation and apoptosis." (PMID 35252353, 2022). "Recently published studies dedicated to other potential urinary protein biomarkers have shown that levels of some of them (EN2, αHGF, IGFBP3, ZAG) are elevated in PCa, while the urinary ANXA3, PAP, and PSA have inverse relationship with cancer." (PMID 33791193, 2020). "Due to the important roles of Annexin A3 and HIF-1α in cancer progression, the correlation between Annexin A3 and HIF-1α expression was analyzed." (PMID 24260057, 2013). "Despite the substantial body of evidence on its tumorigenic role, the precise upstream and downstream signaling transduction of ANXA3 remains incompletely elucidated, and there is a lack of mechanistic studies on the role of ANXA3 in highly prevalent cancers." (PMID 34355022, 2021). "Annexin A3 (ANXA3) is dysregulated and plays an important role in various cancers." (PMID 29374148, 2018). "Although its expression in cancer tissue was not particularly strong, ANXA3 did increase an average 1.2-fold in cancer tissue relative to the normal counterpart as assessed by semi-quantitative assessment." (PMID 29423100, 2018). "However, no previous studies have investigated the correlation between Annexin A3 and HIF-1α expression in types of human cancer." (PMID 24260057, 2013). "However, cancer autoantigenic properties of ANXA3 have not previously been described." (PMID 29423100, 2018). "Therefore, Annexin A3 and HIF-1α have been hypothesized to be vital in the angiogenesis of cancer." (PMID 24260057, 2013). "We also identified the upregulation of DAZL and ANXA3 (data not shown), genes previously reported to be induced by 5-aza-dC, NDN, reported to be imprinted, and MT1G, reported to be methylated in other cancers." (PMID 22984426, 2012).